PINK1 (PTEN induced kinase 1)
Diseases named in the same sentence as PINK1 in open-access papers (continued):
Sharing a sentence is not in itself a finding about the gene and the disease.
liver cancer (12 papers, 2019 to 2025). An epithelial or non-epithelial malignant neoplasm that arises from the liver. "Proteasome inhibitor ONX0912 activates Parkin/PINK1-mediated mitophagy to trigger apoptosis in liver cancer cells." (PMID 40761374, 2025). "Alantolactone, another compound, demonstrates therapeutic potential in liver cancer by suppressing PINK1/Parkin-mediated mitophagy." (PMID 40655944, 2025). "Matrine, a natural alkaloid, accelerated the apoptosis of liver cancer cells by intercepting the PINK1/Parkin pathways and restraining mitophagy." (PMID 37700273, 2023). "A study in mouse hepatic cancer reported that thyroid hormone T3 restrains carcinogenesis through activating the PINK1/Parkin pathway." (PMID 34225732, 2021). "For instance, one report showed that Matrine induces liver cancer cell apoptosis by inhibiting the PINK1/Parkin pathway and mitophagy." (PMID 31551778, 2019). "Interestingly, our recent study showed that the knockout of ATAD3A using Crispr/Cas9 genetic editing in the human liver cancer cell line HuH7 dramatically reduced levels of PINK1, which suggests that ATAD3A interacts with PINK1 differently in different cells." (PMID 37569886, 2023). "Similarly, in renal and liver cancer cells, sorafenib (a multikinase inhibitor) enhanced the occurrence of apoptosis via the mitophagy mediated by PINK1/Parkin pathway." (PMID 36200262, 2022). "In addition, sorafenib stimulates the apoptosis of liver cancer cells through PINK1/Parkin-mediated mitophagy." (PMID 34225732, 2021). "HEY1 overexpression, PINK1 down-regulation, and their correlation were also observed in intrahepatic cholangiocarcinoma (ICC), another type of primary liver cancer which is derived from bile duct." (PMID 31819034, 2019). "As sorafenib was reported to stabilize PINK1 on the OMM to target and inhibit the electron transport chain in mitochondria, and activate the recruitment of Parkin by mitochondria to start mitophagy to treat liver cancer." (PMID 36200262, 2022). "More strikingly, linear regression model showed that HEY1 and PINK1 mRNA expressions were reversely correlated in 72 cases of kidney cancer and non-tumorous tissues, suggesting that our findings are not restricted to liver cancers." (PMID 31819034, 2019).
melanoma (12 papers, 2017 to 2025). A malignant, usually aggressive tumor composed of atypical, neoplastic melanocytes. "However, the precise mechanisms underlying the PINK1’s involvement in melanoma development necessitate further investigation." (PMID 40860809, 2025). "In melanoma cells, the knockdown of PINK1 inhibits BAY 87-2243, a potent inhibitor of the first oxidative phosphorylation complex)-induced reactive oxygen species (ROS) accumulation, mitophagy, and cell death." (PMID 40860809, 2025). "In melanoma, PARK6 regulates proliferation through the PI3K/AKT pathways independent of the PINK1/Parkin pathway." (PMID 40860809, 2025). "BAY 87-2243 (inhibitor of complex I (CI) of the mitochondrial respiratory chain)-induced Pink1-dependent mitophagy is responsible for melanoma cell death." (PMID 34072333, 2021). "Importantly, the uncoupler, FCCP (which dissipates ΔΨm), also stabilizes FL-PINK1 in PTENWT melanoma cells, demonstrating that these cells are capable of proteolytic cleaving of PINK1." (PMID 28092677, 2017). "This suggesting that PINK1 may also influence melanoma progression through this pathway." (PMID 40860809, 2025). "Moreover, PINK1 is known to be induced by the PTEN pathway, which has previously been shown to be involved in melanoma progression and BRAF inhibitor resistance." (PMID 28173755, 2017).
osteoarthritis (12 papers, 2019 to 2025). A noninflammatory degenerative joint disease occurring chiefly in older persons, characterized by degeneration of the articular cartilage, hypertrophy of bone at the margins and changes in the synovial membrane. "In summary, we demonstrated that PPARγ activation inhibits chondrocyte ferroptosis in osteoarthritis and that this chondroprotective effect is associated with the activation of Pink1/Parkin-dependent mitophagy." (PMID 37620972, 2023). "β-Hydroxybutyrate enhances chondrocyte mitophagy and reduces cartilage degeneration in osteoarthritis via the HCAR2/AMPK/PINK1/Parkin pathway, and it alleviates cartilage senescence through the hnRNP A1-mediated upregulation of PTEN." (PMID 40027098, 2025). "Osteoarthritis: PARP12↑ → binds ISG15 → ↑MFN1/2 isoprenylation → inhibits PINK1/Parkin‐mediated mitophagy → promotes cartilage degradation." (PMID 40904702, 2025). "For instance, in osteoarthritis rats, the expression level of PINK1/Parkin significantly decreased when compared with control, while curcumin exerted chondroprotective effects against osteoarthritis by promoting PINK1/Parkin-mediated mitophagy." (PMID 36750550, 2023). "In osteoarthritis progression, a study has reported that activation of the PINK1/parkin pathway accelerates mitophagy, contributing to the maintenance of mitochondrial homeostasis and the alleviation of chondrocyte injury." (PMID 37749650, 2023). "A previous study has shown that models of osteoarthritis exhibit an augmentation in the expression of PINK1 and Parkin." (PMID 38004411, 2023). "It was reported that metformin protects against osteoarthritis through PINK1/Parkin-dependent mitophagy by up-regulating SIRT3 expression." (PMID 36387221, 2022). "The data presented here confirm the strong link between mitophagy and osteoarthritis, with Pink1 expression serving as an important regulator of mitophagy-related cartilage degeneration." (PMID 31684073, 2019). "Matrix stiffening downregulates HDAC3 to activate phosphatase and tensin homolog-induced kinase 1 (PINK1) and Parkin (PINK1/Parkin) mediated mitophagy, thereby stimulating chondrocyte senescence and accelerating the initiation and progression of osteoarthritis." (PMID 38789434, 2024). "Further understanding of the pathophysiology linking mitophagy-induced cartilage damage and Pink1 expression may pave the way for targeted osteoarthritis treatments." (PMID 31684073, 2019). "In vivo results showed that SND1 silencing inhibited SND1, PINK1 and BECN1 proteins expression in rat knee cartilage tissues compared with the osteoarthritis rats." (PMID 37749650, 2023).
non-small cell lung carcinoma (11 papers, 2019 to 2025). A group of at least three distinct histological types of lung cancer, including non-small cell squamous cell carcinoma, adenocarcinoma, and large cell carcinoma. "PINK1 was found to be elevated PINK1 was found to be elevated in non-small cell lung cancer and was linked to mitochondrial dysfunction." (PMID 37833780, 2023). "In vitro studies have demonstrated that PINK1 promotes the proliferation of non-small cell lung cancer cells, and PINK1 expression is associated with stronger tumour invasion and poor prognosis." (PMID 36823640, 2023). "The overexpression of PINK1 activates NF-κB signaling and promotes the development of non-small-cell lung cancer (NSCLC)." (PMID 34751247, 2021). "Similarly, targeting PINK1-mediated mitophagy enhances the efficacy of cisplatin in non-small cell lung cancer by preventing the clearance of damaged mitochondria." (PMID 39859167, 2025). "PINK1 overexpression promoted the proliferation of non-small cell lung cancer cells." (PMID 36909198, 2023). "Pink1 downregulation promotes cisplatin-induced apoptosis in non-small cell lung cancer cells." (PMID 36289190, 2022). "Besides, PINK1 may contribute to chemoresistance in non-small cell lung cancer." (PMID 37047483, 2023). "In non-small-cell lung cancer (NSCLC), PINK1 downregulation potentiates cisplatin-induced NSCLC cell apoptosis, and similar results have been obtained in esophageal squamous cell carcinoma (ESCC) patients undergoing neoadjuvant chemotherapy." (PMID 33946271, 2021).
pancreatic cancer (11 papers, 2019 to 2025). "In KRAS-driven pancreatic cancer, loss of either Parkin or PINK1 increases tumor burden and metastasis, suggesting that these proteins play an early tumor-suppressive role through mitochondrial maintenance." (PMID 41138746, 2025). "Genetic ablation of Pink1 or Park2 in mice increased susceptibility to oncogenic Kras-driven pancreatic cancer development." (PMID 32703253, 2020). "Morever, dysregulation of the PINK1/PARK2 axis accelerates KRAS-mediated carcinogenesis in pancreatic cancer." (PMID 33139776, 2020). "PINK1-PRKN/PARK2-mediated mitophagy has also been reported to suppress pancreatic tumor growth through the autophagic degradation of mitochondrial iron importers, including SLC25A37 and SLC25A28." (PMID 32703253, 2020). "In conclusion, STOML2 could stabilize PARL and promote PINK1 degradation, which represses mitophagy and ultimately reduces chemoresistance in pancreatic cancer." (PMID 36906621, 2023). "Of note, high expression of PRKN mRNA was found to be associated with improved survival of pancreatic cancer patients, whereas mRNA expression of PINK1 did not influence patient survival, indicating that PINK1 is a contributor of PDAC, but it is not a potential biomarker." (PMID 33718171, 2021). "Here, we report the CuB-induced mitophagy of pancreatic cancer via the PI3K/Akt/mTOR and PINK1/Parkin pathways, subsequently modulating the key enzyme levels in the glycolysis pathway and reducing the energy supply for pancreatic cancer cells." (PMID 40944197, 2025). "Hence, GEM could promote PINK1-induced mitophagy in pancreatic cancer cells." (PMID 36906621, 2023). "Therefore, we reveal that CuB can induce cellular mitophagy, inhibit glycolysis in pancreatic cancer cells, and improve the TME in terms of metabolic balance through the PI3K/Akt/mTOR and PINK1/Parkin pathways and LDHA downregulation." (PMID 40944197, 2025). "Because the expression of full-length PINK1 was low in the general state, we employed carbonyl cyanide m-chlorophenylhydrazone (CCCP) (10 μM) to elevate PINK1 levels, making it suitable to observe the effects of STOML2 on PINK1 in pancreatic cancer cells." (PMID 36906621, 2023). "In conclusion, our study found that STOML2 could repress PINK1-induced mitophagy by directly stabilizing PARL, thus inhibiting pancreatic cancer chemoresistance." (PMID 36906621, 2023). "In addition, Parkin is regulated by PINK1 in normal cells, but it is not involved in Pink1-dependent mitophagy in pancreatic cancer cells." (PMID 36831455, 2023). "Consequently, in vitro or xenograft mouse models show that the genetic depletion of STING1 or MFN1/2 (but not the mitophagy regulator PINK1 or PRKN) reduces the sensitivity of pancreatic cancer cells to ferroptosis." (PMID 34195205, 2021).
asthma (10 papers, 2020 to 2025). "Conclusively, DEK deficiency alleviates airway inflammation in asthma by down-regulating PINK1-Parkin mitophagy, NLRP3 inflammasome activation, and apoptosis." (PMID 38274803, 2023). "Compared with the healthy control group, the mRNA and protein levels of PINK1 and Parkin in bronchial epithelial cells, lung tissue, and airway fibroblasts of asthma patients were significantly increased." (PMID 41026942, 2025). "This phenomenon was further verified in the lung tissue of an asthma mouse model induced by ovalbumin, suggesting that PINK1-Parkin-mediated mitophagy is the core response mechanism of asthma pathophysiology." (PMID 41026942, 2025). "The mechanism of PINK1-Parkin-mediated NLRP3 inflammasome activation in asthma is largely controversial." (PMID 38274803, 2023). "PINK1, parkin, and other mitophagy-related proteins are upregulated in fibroblasts from patients with asthma." (PMID 35747690, 2022). "Immunohistochemical evaluation of bronchial biopsies showed intense PINK1 immunoreactivity in severe asthma than in control." (PMID 32670268, 2020). "In order to assess PINK1 processing and its stability in severe asthma, the levels of PINK1 protein was determined in S-As and control fibroblasts at 12 and 24 hours using western blot analysis." (PMID 33253229, 2020). "Studies have shown that the PINK1-Parkin pathway generally shows an up-regulated trend in asthma." (PMID 41026942, 2025). "During asthma process, miR-423 downregulated the expression of interleukin-1β/NOD-like receptor thermal protein domain associated protein 3/Caspase-1 inflammasome signaling by targeting PINK1 in lung cells." (PMID 39276929, 2024). "For further validation of the role of mitochondrial dysfunction in asthma progression, we next performed immunohistochemical staining of PINK1 on bronchial biopsies obtained from a cohort of six patients with severe asthma compared to 2 biopsies obtained from healthy control subjects." (PMID 32670268, 2020). "However, the regulation of PINK1-Parkin-mediated mitophagy by DEK in asthma remains largely unknown." (PMID 38274803, 2023). "Therefore, targeting DEK to downregulate PINK1-Parkin-mediated mitophagy may offer an effective approach for preventing and treating airway inflammation in asthma." (PMID 38274803, 2023). "The observed increase in autophagy and PINK1 immunoreactivity in S-As fibroblasts may be attributed to their prolonged exposure to increased levels of IL-17, which is known to be upregulated in the airway tissue microenvironment in severe asthma." (PMID 32670268, 2020). "Based on these previous findings and our findings, we conclude that PINK1-Parkin-mediated mitophagy can promote NLRP3 inflammasome pathway activation and apoptosis in HDM-induced asthma." (PMID 38274803, 2023). "Herein, we investigated the regulation of DEK on the PINK1-Parkin pathway, NLRP3 inflammasome, and apoptosis in the HDM-induced asthma model." (PMID 38274803, 2023). "This study is the first to identify a hitherto uncharacterized mechanism, i.e. the DEK/ATAD3A/DRP1 signaling axis, by which DEK promotes PINK1-Parkin mitophagy, NLRP3 inflammasome activation, and aggravates airway inflammation in asthma." (PMID 38274803, 2023). "DEK gene knockout, silencing, and targeted inhibitors down-regulated PINK1-Parkin-mediated mitophagy, NLRP3 inflammasome activation, and apoptosis, thereby improving airway inflammation in asthma." (PMID 38274803, 2023). "Likewise, IL-25 is elevated in asthma and improves mitophagy and CCL-22 secretion in monocytes; moreover, inhibition of mitophagy by PINK1 knockdown reduces the production of CCL-22." (PMID 37181813, 2023). "Although mitophagy-related proteins such as PINK1, BNIP3, and FUNDC1 typically exhibit compensatory up-regulation in various pathologies, their expression is significantly reduced in nasal polyp tissues of asthma patients with chronic rhinosinusitis with nasal polyps (CRSwNP)." (PMID 41026942, 2025).
chronic obstructive pulmonary disease (10 papers, 2016 to 2025). A chronic and progressive lung disorder characterized by the loss of elasticity of the bronchial tree and the air sacs, destruction of the air sacs wall, thickening of the bronchial wall, and mucous accumulation in the bronchial tree. "For example, it has been reported that Parkin-Pink1-mediated mitophagy contributes to necroptosis and pathology in chronic obstructive pulmonary disease (COPD)." (PMID 33728026, 2021). "Moreover, NEAT1 also increases PINK1 and parkin expression, thereby enhancing lung mitophagy in chronic obstructive pulmonary disease." (PMID 36430876, 2022). "Moreover, both PINK1 and PARK2 contribute to the regulation of mitochondrial autophagy, control of mitochondrial ROS, and modulation of lung EC death and senescence, playing crucial roles in the pathogenesis of IPF and chronic obstructive pulmonary disease (COPD)." (PMID 40901482, 2025). "In contrast, mitophagy protein PINK1 cannot eliminate the effects of PRKN, which indicates that mitophagy protein PRKN plays a key role in regulating mitochondrial autophagy and the pathogenesis of chronic obstructive pulmonary disease (COPD)." (PMID 35321239, 2022). "In chronic obstructive pulmonary disease (COPD) cigarette smoking triggers a form of autophagy, namely mitophagy (autophagy-dependent selective elimination of mitochondria), through stabilization of the mitophagy regulator PINK1 (PTEN-induced putative kinase 1)." (PMID 26222012, 2016).
Dyskinesia (10 papers, 2019 to 2025). A movement disorder which consists of effects including diminished voluntary movements and the presence of involuntary movements. "Limited data support that PINK1 mutation carriers show a transient therapeutic benefit after surgery; however, in the long-term follow-up they developed axial symptoms and dyskinesia and were almost unresponsive to drug therapy and neurostimulation." (PMID 39199492, 2024). "In some PINK1 patients, dyskinesias are reported early after levodopa is started, while others show a good response for many years before fluctuations and dyskinesias start." (PMID 34831247, 2021). "Limited data support that PINK1 mutation carriers show a transient therapeutic benefit after surgery; however, they developed axial symptoms and dyskinesia, and were almost not responsive to drug therapy and neurostimulation." (PMID 39199492, 2024). "For example, PINK1 deficiency was found to result in mitochondrial swelling, reduced cristae, and mitochondrial fission dependent on DRP1 regulation in PINK1 knockout rats, with a slow onset and progression of dyskinesia, similar to that described in the PD phenotype." (PMID 40002740, 2025). "PRKN and PINK1 mutation carriers also reported more postural problems at diagnosis than non-carriers and tended to report a higher rate of dyskinesias, after adjusting for age at entry, gender, disease duration and LEDD total, although this did not survive correction for multiple testing." (PMID 31324919, 2019). "The case presented a PRKN/PINK1‐related EOPD with a lower AAO, slower development, early dyskinesia, and a favorable response to levodopa and STN DBS." (PMID 40898742, 2025). "Genetic factors are more commonly observed in LD‐induced dyskinesias, such as LRRK2, PARK2 (parkin), PARK6 (pink‐1), and PARK7 (DJ‐1)." (PMID 40785408, 2025).
idiopathic pulmonary fibrosis (10 papers, 2015 to 2025). Idiopathic pulmonary fibrosis (IPF) is a nonneoplastic pulmonary disease that is characterized by the formation of scar tissue within the lungs in the absence of any known cause. "Similarly, PINK1 deficiency induced mtDNA release in type II alveolar epithelial cells (AECII) in a model of idiopathic pulmonary fibrosis (IPF)." (PMID 40264103, 2025).